IDH1 (isocitrate dehydrogenase (NADP(+)) 1)
Diseases named in the same sentence as IDH1 in open-access papers (continued):
Sharing a sentence is not in itself a finding about the gene and the disease.
biliary tract cancer (16 papers, 2020 to 2024). "In a cohort of 34 patients with biliary tract cancer, actionable variants were detected in IDH1/2 (18%), followed by FGFR1/2 (16%), EGFR or ERBB2/3 (16%), PTEN (14%), MDM2 (10%), and PIK3CA (10%)." (PMID 36290850, 2022). "Although the difference in progression-free survival (PFS) is relatively small, it implies that a new treatment option exists for patients with IDH1/2 mutations who constitute a certain proportion of biliary tract cancer cases." (PMID 33562094, 2021). "Among biliary tract cancers, however, several studies have shown that IDH1 mutations nearly exclusively occur in ICC." (PMID 34945742, 2021). "When we explored cBioPortal for IDH1/2 mutations in biliary tract cancers (n = 182), including gallbladder cancer, IDH1 and IDH2 mutations were found to be restricted to codon 132 and codon 172, respectively." (PMID 32978444, 2020). "In a randomized phase III study enrolling 230 patients with IDH1 mutated biliary tract cancer, ivosidenib, an oral inhibitor of mutated IDH1, significantly improved progression-free survival compared with the placebo (2.7 months vs. 1.4 months, hazard ratio 0.37, p < 0.0001)." (PMID 36290850, 2022). "For example, molecular abnormalities such as IDH1/2 mutations, FGFR2 fusions, and HER-2 overexpression are more common in some types of biliary tract cancer." (PMID 39839773, 2024). "Currently potential therapeutic targets have been identified in nearly 40% of biliary tract cancers, with the most promising in iCCA patients including isocitrate dehydrogenase 1 (IDH1) and fibroblast growth factor receptor 2 (FGFR2)." (PMID 37168376, 2023). "Multiple studies have assessed the ability of certain biomarkers, such as BRCA in pancreatic cancer, IDH1 or FGFR2 in biliary tract cancer and microsatellite instability or NTRK fusions in an agnostic tumour fashion, to predict response to treatment." (PMID 36008616, 2022). "Targeted therapies (ie, FGFR2 and IDH1 inhibitors) have a potential role in the second-line setting for advanced biliary tract cancer." (PMID 33798493, 2021). "Recently, several targeted therapies have been investigated in advanced biliary tract cancer (BTC) including inhibitors of genes or pathways such as FGFR2 fusions or rearrangements, IDH1 mutations, and NTRK gene fusions." (PMID 35693217, 2021). "IDH1/2 mutations are biomarkers with a good prognosis in brain tumours but are not related to the prognosis in biliary tract cancer." (PMID 33562094, 2021). "Driver genes, such as the ERBB2, PIK3CA, IDH1/2, BRCA1/2, and FGFR2 fusion genes, have been identified in gallbladder and biliary tract cancers." (PMID 34573929, 2021). "Whereas in iCC alterations in genes dedicated as ESCAT I/II (FGFR2 fusion, BRAF-V600E mut., Her2neu amplification, IDH1 mut., MSI and NTRK Fusion) according to the latest ESMO guidelines for molecular testing in biliary tract cancer were more frequent than in eCC (27.5% vs. 10.5%; p = 0.0093)." (PMID 37723192, 2023).
myeloproliferative neoplasm (16 papers, 2012 to 2024). A clonal hematopoietic stem cell disorder, characterized by proliferation in the bone marrow of one or more of the myeloid (i.e., granulocytic, erythroid, megakaryocytic, and mast cell) lineages. "We aimed to determine the genotype distribution, allele frequency, and prognostic impact of IDH1/2, TET2, and ASXL1 single nucleotide polymorphisms (SNPs) in myeloproliferative neoplasms (MPNs)." (PMID 28218607, 2017). "IDH1 and IDH2 mutations were also identified in chronic myeloid neoplasms, including MDS and myeloproliferative neoplasms (MPNs)." (PMID 26668680, 2016). "In patients with myeloproliferative neoplasms characterized by JAK2 and IDH1/2 mutations, it is tempting to speculate that these gene mutations have an additive or cooperative effect to facilitate leukemogenesis." (PMID 23847760, 2013).
medulloblastoma (15 papers, 2015 to 2025). A malignant, invasive embryonal neoplasm arising from the cerebellum. "Interestingly, one of the cases (MB_2) was a rare SHH-activated medulloblastoma showing an IDH1:p.R132C mutation." (PMID 32758285, 2020). "It has been widely applied to predict IDH1 mutational status and medulloblastoma subgrouping." (PMID 28915860, 2017). "We show that most cases will likely be resolved by careful histopathologic analysis and the use of immunohistochemical stains, including surrogate stains for histone 3, IDH1 and BRAF mutations, and subtype-specific stains for ependymoma and medulloblastoma." (PMID 38764578, 2024). "We report concurrent IDH1 and SMARCB1 mutations in a medulloblastoma patient." (PMID 29971034, 2018).
pancreatic cancer (15 papers, 2014 to 2025). "In the future, NGS will have a greater impact on CDM, as targeted treatment options for CCA and pancreatic carcinoma expand, including US Food and Drug Administration-approved options for mutations in theFGFRpathway,IDH1,ERBB2,BRCA1/2, and microsatellite-instable tumors." (PMID 40932825, 2025). "Together, these experiments point to IDH1 as an enzyme critical for pancreatic cancer adaptation to oxidative stress." (PMID 35681100, 2022). "Our recent studies in pancreatic cancer identified for the first time that small molecules developed as selective mutant-IDH1 inhibitors, actually inhibit wtIDH1 with a high degree of potency under conditions present in the tumor microenvironment." (PMID 36153582, 2022). "Wild-type IDH1 genetic sequence was confirmed in murine pancreatic cancer cell line KPC K8484." (PMID 35681100, 2022). "Winter and colleagues demonstrate that metabolic adaptation to nutrient stress in the tumor microenvironment of pancreatic cancer leads to a dependency on IDH1, which is therapeutically actionable regardless of IDH1 mutation status." (PMID 35681100, 2022). "However, a recent study demonstrated that a high expression level of IDH1 was observed in primary and metastatic pancreatic cancers." (PMID 32110969, 2020). "Furthermore, the Food & Drug Administration (FDA)-approved mIDH1 inhibitor ivosidenib (AG-120) dramatically inhibited tumor growth in preclinical models of pancreatic cancer, highlighting this approach as a potential therapeutic strategy against wild-type IDH1 cancers." (PMID 35681100, 2022). "Thus, even though triptolide decreased hypoxia, it also affected the general metabolic pathways in the pancreatic cancer cells leading to decreased IDH1 activity, leading to a decreased synthesis of αKG, which in turn decreased PHD enzyme activity causing an accumulation of HIF-1α in the cells." (PMID 28801636, 2017).
angioimmunoblastic T-cell lymphoma (13 papers, 2014 to 2025). A mature T-cell non-Hodgkin lymphoma, characterized by systemic disease and a polymorphous infiltrate involving lymph nodes and extranodal sites. "In myeloid neoplasms, TET2 and IDH1/2 mutations are usually mutually exclusive, but they are often paired together in Angioimmunoblastic T-cell Lymphoma (AITL)." (PMID 33520997, 2020). "In a clinical study, IDH1 and IDH2 mutations were observed in 16%–17% of patients with AML, in around 20% of angioimmunoblastic T-cell lymphomas (AITL) with worse prognosis, and in some low-frequency cancer malignancies." (PMID 31817761, 2019).
gastric cancer (13 papers, 2014 to 2024). A primary or metastatic malignant neoplasm involving the stomach. "Mining of the Cosmic database revealed only one reported IDH1 c.941G>A/p.R314H mutation in a gastric carcinoma (mutation ID COSM4090677)." (PMID 27460417, 2016). "R132H and R132C missense mutations in the IDH1 gene were observed, and are the first reported mutations of their kind in gastric carcinoma." (PMID 25656989, 2015). "Isocitrate dehydrogenase (IDH1) expression has been shown to be essential for the survival of gastric cancer cells." (PMID 38406279, 2024). "Drugs targeting wild-type IDH1 could be clinically helpful in some gastric cancers." (PMID 38406279, 2024). "Besides, IDH1 and MUC16 mutations are associated with an improved prognosis in gastric cancer." (PMID 36900401, 2023). "We also revealed that IDH1 and IDH2 modulate 5hmC levels in human gastric cancer." (PMID 29661250, 2018).
fibrosarcoma (12 papers, 2012 to 2025). A malignant mesenchymal fibroblastic neoplasm affecting the soft tissue and bone. "Consistent with this notion, the levels of D-2HG in fibrosarcoma cells, HT-1080, which harbor one of the most common IDH1 mutations, IDH1R132C, were more than 30 fold higher compared to cells harboring the SLC25A1-KD." (PMID 39733217, 2025). "The d-2-HG biosensor Bd2HG-1 could detect the increase in d-2-HG levels in the cell culture medium during the growth of HEK293FT cells transfected with IDH1/R132H and of HT1080 cells, a fibrosarcoma cell line carrying an IDH1/R132C mutation." (PMID 34876568, 2021). "Our new results proved the role of mTOR activity and the inhibitory effect of rapamycin both in lactate and in 2-HG oncometabolite productions of heterozygous IDH1 mutant fibrosarcoma cells." (PMID 28578659, 2017). "Our results showed that the endogenous mutant IDH1 expressing HT-1080 fibrosarcoma cells with glycolytic phenotype proved to be a suitable model to characterise the role of mTOR in the regulation of 2-HG and lactate productions." (PMID 28578659, 2017). "To address this issue, we studied HT1080, a fibrosarcoma cell line carrying a native IDH1R132C heterozygous mutation, and found that selectively knocking down mutant IDH1 inhibited cell growth." (PMID 22885298, 2012). "Here, using a genetically engineered inducible system, we report that selective suppression of endogenous mutant IDH1 expression in HT1080, a fibrosarcoma cell line with a native IDH1R132C heterozygous mutation, significantly inhibits cell proliferation and decreases clonogenic potential." (PMID 22885298, 2012).
lung adenocarcinoma (12 papers, 2015 to 2025). A carcinoma that arises from the lung and is characterized by the presence of malignant glandular epithelial cells. "IDH1/2 mutations have also been associated with extensive smoking history in patients with lung adenocarcinoma." (PMID 32856857, 2020). "In this study, the high incidence of coexisting KRAS and EGFR driver mutations and the lower than expected IDH1/2 VAF suggest that IDH1/2 mutations may be branching drivers promoting subclonal progression of lung adenocarcinomas." (PMID 32333643, 2020). "In addition, IDH1/2 mutations in lung adenocarcinoma are considered uncommon events." (PMID 34684076, 2021). "We obtained detailed treatment and survival data of 8 patients with active‐site IDH1/2 mutations and found that seven of them (87.5%) showed high‐grade features (stage IV), whereas the other patients exhibited resectable stage III lung adenocarcinoma." (PMID 35526267, 2022). "Studies in lung adenocarcinoma patients show increased expression levels of wild-type IDH1, CD44, and reduced glutathione." (PMID 36497259, 2022). "Extensive clear cell change has been previously reported in lung adenocarcinomas with either IDH1 p.R132C or p.R132L mutation, but not in nine lung adenocarcinomas in this study, including four with an IDH1 p.R132L mutation." (PMID 32333643, 2020). "IDH1 p.R132C also shows a relatively higher effect size (104‐105) in lung adenocarcinomas." (PMID 32333643, 2020). "Lower than expected variant allele frequency of IDH1/2 mutants and coexistence of IDH1/2 mutations with known trunk drivers in the BRAF, EGFR, and KRAS genes suggest they could be branching drivers leading to subclonal evolution in lung adenocarcinomas." (PMID 32333643, 2020). "Moreover, IDH1 levels in plasma of lung squamous cell carcinoma and lung adenocarcinoma patients were significantly elevated compared to benign lung disease patients and healthy individuals, suggesting IDH1 as a potential plasma biomarker for the diagnosis of NSCLCs." (PMID 31010244, 2019). "IDH1 positively correlates with CD44 and reduced glutathione in lung adenocarcinomas, suggesting a positive effect of IDH1 on tumor growth." (PMID 36497259, 2022). "Previous studies have reported that some proteins including HMGA1, IDH1, CEA and CYFRA play a role in the development of lung adenocarcinoma." (PMID 33424830, 2020).
non-small cell lung carcinoma (12 papers, 2015 to 2024). A group of at least three distinct histological types of lung cancer, including non-small cell squamous cell carcinoma, adenocarcinoma, and large cell carcinoma. "Elevated IDH1 expression, including the common R132H mutations, was found in non-small-cell lung cancer (NSCLC) cells." (PMID 31847543, 2020). "IDH1 protein has been identified as a novel biomarker for the diagnosis of non-small cell lung cancer." (PMID 27863386, 2016). "Importantly, several studies indicate that IDH1 overexpression correlates with poor OS in the non-small cell lung carcinoma (NSCLC) patients adenocarcinoma and squamous cell carcinomas." (PMID 31010244, 2019). "It has been demonstrated that IDH1 expression is induced in non-small-cell lung cancer (NSCLC)." (PMID 30305430, 2018). "In the non-small cell lung cancer model the following 5 DEPs were found to be involved in the GSH metabolism pathway (G6PD, PRDX2, IDH1, MGST1 and 6PGD), 4 DEPs in the PPP pathway (G6PD, TALDO1, TKT and 6PGD) and 1 DEP involved in the glycolysis pathway (ALDH3A1)." (PMID 28303926, 2017).
ovarian carcinoma (11 papers, 2018 to 2025). A malignant neoplasm originating from the surface ovarian epithelium. "However, IDH1 mutations are relatively rare in ovarian cancer, indicating that the cisplatin-sensitizing effects of Ivosidenib may involve non-canonical mechanisms." (PMID 40342735, 2025). "On the other hand, an inverse relationship between BCAT1 and IDH1/2 was found in epithelial ovarian cancer (EOC), where BCAT1 silencing suppressed the expression of IDH1/2 genes." (PMID 29211698, 2018). "In ovarian cancer, wild-type IDH1 was unregulated in TCA cycle metabolism." (PMID 40868085, 2025). "PARPi, which are widely used to treat breast and ovarian cancers carrying BRCA mutations, are now emerging as novel therapeutics for acute leukemia with selected genetic backgrounds; for example, they are effective against IDH1/2- or AML1-ETO-mutant AML cells." (PMID 39175540, 2024). "In ovarian cancer, wild-type IDH1 was upregulated TCA cycle metabolism." (PMID 37110218, 2023). "Interestingly, in 2015, an inverse relationship between BCAT1 and IDH1/2 was found in epithelial ovarian cancer, where BCAT1 knockdown inhibited the expression of IDH1/2." (PMID 32238881, 2020). "Considering their role in TCA cycle, the metabolic link between BCAT1 and IDH1/2 may contribute to elevated cellular migration and invasion in ovarian cancer." (PMID 32238881, 2020). "Through comprehensive screening, we demonstrated that the mutant IDH1 inhibitor ivosidenib significantly enhances the sensitivity of BRCA1/2-proficient breast and ovarian cancer cells to PARP inhibitors (PARPi)." (PMID 40299557, 2025). "Knocking down Bcl2l10 downregulated IDH1 and SDHD and led to the accumulation of oncometabolites, such as succinate and isocitrate, and therefore led to the promotion and progression of ovarian cancer." (PMID 40868085, 2025). "Knocking down Bcl2l10 downregulated IDH1 and SDHD and led to the accumulation of oncometabolites such as succinate and isocitrate, and therefore lead to the promotion and progression of ovarian cancer." (PMID 37110218, 2023). "In addition, through the literature review, we found that except CYBB, VDAC2, IDH1, MT1G, SLC1A4, PCK2, SLC3A2, the prognostic value of other FRGs in ovarian cancer has been reported, which provided a possibility for constructing a prognostic model." (PMID 36386203, 2022).
acute lymphoblastic leukemia (10 papers, 2015 to 2025). Leukemia with an acute onset, characterized by the presence of lymphoblasts in the bone marrow and the peripheral blood. "IDH1 gene mutations occur frequently in AML (acute lymphoblastic leukemia)." (PMID 37863956, 2023). "In contrast to AML, the incidence and prognostic value of IDH1/2 mutations in T-cell acute lymphoblastic leukemia (T-ALL) are poorly reported." (PMID 36614080, 2022). "There is limited knowledge about the incidence of IDH1 and IDH2 mutations in acute lymphoid leukemia (ALL) patients and the prevalence of these mutations in acute leukemia patients in Saudi Arabia." (PMID 34946913, 2021). "The reason could be that IDH1/2 mutations occur more common in FAB M0, which is required to distinguish from acute lymphoblast leukemia in morphologic diagnosis." (PMID 26466372, 2015).
anaplastic oligoastrocytoma (9 papers, 2013 to 2023). An oligoastrocytoma characterized by the presence of increased cellularity, nuclear atypia, pleomorphism, and high mitotic activity. "A 49-year-old male underwent a subtotal resection of a lobular lesion within the right insula in 2013, revealing a WHO grade 3 anaplastic oligoastrocytoma, IDH1 mutated, 1p19q intact." (PMID 37077830, 2023).
bone tumors (9 papers, 2014 to 2025). "Our finding that mutant IDH1 ctDNA was detected in the vast majority of patients with high grade CS harboring an IDH1 mutation indicates that preoperative detection of ctDNA could potentially replace the need for a CT‐guided needle biopsy—the conventional means of obtaining a bone tumor diagnosis." (PMID 28834325, 2017). "For example, only one positively selected gene was detected in bone cancer (IDH1) and nervous system cancer (ALK), respectively." (PMID 28938601, 2017).
brain glioma (9 papers, 2020 to 2024). A malignant glioma that involves the brain. "Nevertheless, the available literature has a limited number of studies investigating the relationship between blood flow measured by ASL perfusion and IDH1 mutations in brain gliomas." (PMID 35741254, 2022). "In the available literature, there are few studies investigating the relationship between blood flow measured by ASL perfusion and IDH1 mutation in brain gliomas." (PMID 35741254, 2022). "Among the 10 patients on which biomolecular studies were performed, eight showed positive IDH1 R132H mutations in the brain glioma; in three of them, this mutation was simultaneously detected in the enchondroma." (PMID 35884525, 2022). "In gliomas of the brain, IDH1/2 mutations are trunk drivers to confer cancer initiation and are favorable prognostic markers." (PMID 32333643, 2020). "As expected, mutations of IDH1 codon 132 show a very high effect size (greater than 106 or 107) in lower‐grade glioma of the brain." (PMID 32333643, 2020). "The most of IDH1/2-mutant brain gliomas affected adults, there is evidence that IDH1/2 mutations are possibly involved with the progression of brain gliomas from grade II to grade III." (PMID 32784466, 2020). "To study the relationship between TBF determined by pseudo-continuous ASL perfusion and IDH1 status, we analyzed data from 106 patients with brain gliomas." (PMID 35741254, 2022). "ASL perfusion may be an informative factor in determining the IDH1 status in brain gliomas preoperative and tumor proliferative activity." (PMID 35741254, 2022).